MCPH1 (microcephalin 1)
Description:
Implicated in chromosome condensation and DNA damage induced cellular responses. May play a role in neurogenesis and regulation of the size of the cerebral cortex.
Synonyms: FLJ12847; BRIT1; MCT
Tractability: PROTAC: ubiquitination databases record sites on it.
Gene: Protein-coding gene on chromosome 8 (6,406,592 to 6,648,508, forward strand). Ensembl gene ENSG00000147316.
Subcellular location: Cytoplasm, cytoskeleton, microtubule organizing center, centrosome
Pathways (Reactome):
Cell Cycle: Condensation of Prophase Chromosomes
Gene Ontology:
Molecular function: identical protein binding; protein binding
Biological process: negative regulation of transcription by RNA polymerase II; mitotic cell cycle; cerebral cortex development; regulation of gene expression
Cellular component: nucleoplasm; centrosome
Genetic constraint (gnomAD): Loss-of-function variants: 85 observed, 75.87 expected, observed/expected ratio (o/e) 1.12, 90% interval 0.94 to 1.34. The synonymous counts are far from expectation, so gnomAD's model fits this gene poorly and the ratio says little. Missense variants: 1,346 observed, 948.45 expected, observed/expected ratio (o/e) 1.42, 90% interval 1.36 to 1.48. Synonymous variants: 467 observed, 352.78 expected, observed/expected ratio (o/e) 1.32, 90% interval 1.23 to 1.43.
Gene-disease validity (ClinGen):
ClinGen rates the evidence that MCPH1 causes each of these diseases.
microcephaly with intellectual disability (autosomal recessive): Definitive. Microcephaly characterized by both microcephaly and atypical neurodevelopment, without other commonly reported non-brain related phenotypes.
hereditary breast carcinoma (autosomal dominant): Limited. Breast carcinoma that has developed in relatives of patients with history of breast carcinoma.
familial ovarian cancer (autosomal dominant): No Known Disease Relationship. An instance of ovarian cancer that is caused by an inherited modification of the individual's genome.
Homologues: Orthologues: chimpanzee MCPH1 (97% identical), macaque MCPH1 (92% identical), dog MCPH1 (63% identical), pig MCPH1 (61% identical), rabbit MCPH1 (59% identical), mouse Mcph1 (57% identical), rat Mcph1 (56% identical), guinea pig MCPH1 (54% identical), tropical clawed frog mcph1 (33% identical), zebrafish mcph1 (25% identical), Drosophila melanogaster MCPH1 (22% identical).
Diseases named in the same sentence as MCPH1 in open-access papers:
MCPH1 is named in the same sentence as 103 diseases in open-access papers, as found by Europe PMC text mining. Sharing a sentence is not in itself a finding about the gene and the disease. The quoted sentences say what the papers report.
microcephaly (71 papers, 2009 to 2025). A congenital or acquired developmental disorder in which the circumference of the head is smaller than normal for the person's age and sex. "MCPH1 regulates the DNA-damage response and is associated with microcephaly and neurological function." (PMID 40790240, 2025). "A pathogenic missense variant in MCPH1 p.Gly753Arg, and two pathogenic frameshifts MCPH1 p.Asn189LysfsTer15 and p.Cys624Ter identified in this study, already had entries in ClinVar and were associated with microcephaly." (PMID 38463519, 2024). "Causal mutations in the MCPH1 gene have been associated with disorders like microcephaly, and recently congenital hearing impairment." (PMID 38463519, 2024). "The most current research has focused on the mechanism of MCPH1 causing microcephaly while ignoring another phenotype in MCPH1 patients." (PMID 38731817, 2024). "To understand this association, we studied the role of the microcephaly gene Mcph1 in hematological development." (PMID 38605277, 2024). "These mutants successfully reproduced the characteristics of primary microcephaly caused by the human MCPH1 mutation." (PMID 38731817, 2024). "Of note in this context, deletion of Mcph1 in mice, which encodes microcephalin, results in microcephaly because of a premature switch from symmetric to asymmetric division of CSPCs." (PMID 38075281, 2023). "All common mutations causing microcephaly are present in genes implicated in cell division (MCPH1, ASPM, CDK5RAP2, CENPJ, STIL, WDR62, and CEP152)." (PMID 37294214, 2023). "It is important to emphasize that the term “MCPH” is often used for autosomal recessive non-syndromic microcephaly only (see MIM #251200, MCPH1), which is characterized by microcephaly and intellectual deficiency; in some patients, short stature was present." (PMID 36831309, 2023). "Another autosomal recessive condition of microcephaly associated with craniofacial abnormalities was later found to be caused by mutations in the same MCPH1 gene." (PMID 35053391, 2022). "Mutations in the N-terminal and central domains of MCPH1 are strongly associated with microcephaly in human patients." (PMID 36078123, 2022). "For example, two heterozygous missense mutations (C.982G > A and C.1273T > A) in exon 8 of MCPH1 were found in microcephaly individuals of a Saudi family." (PMID 36078123, 2022). "When MCPH1 is mutated, the defects in mitochondrial structure and metabolism lead to a reduction in cell proliferation and survival and finally to microcephaly." (PMID 35069108, 2021). "First transgenic macaques, with mutated MCPH1 and modeling human microcephaly, have been recently generated." (PMID 35069108, 2021). "Cells derived from patients affected by microcephaly caused by mutations in the MCPH1 gene undergo premature chromosome condensation." (PMID 34850681, 2021). "Several other DNA damage response proteins, which are binding partners of BRCA1 (such as SLX4, TOP3A, RNF168, and MCPH1) are also associated with microcephaly." (PMID 33441416, 2021). "Using mouse models of Mcph1 mutations, it was shown that microcephaly can develop due to the premature differentiation of neurons." (PMID 32498399, 2020). "Twelve microcephaly genes, microcephalin-1 (MCPH1)-MCPH12, have been mapped; many of which encode for proteins localized at the centrosome or proteins associated with centrosomal-related activities." (PMID 32498399, 2020). "Microcephalin 1 (MCPH1) was identified from genetic mutations in patients with primary autosomal recessive microcephaly." (PMID 32735676, 2020). "MCPH1-deleted cells displayed prophase-like nuclei suggestive of the PCC phenotype previously observed in primary microcephaly patients bearing MCPH1 mutations." (PMID 33203878, 2020). "Tcf4 binds together with microcephaly-associated transcription factors Smad4, Sox2, Chd7 and Ep300 to active enhancers at primary microcephaly genes Mcph1 and Wdr62." (PMID 28375211, 2017).
microcephaly (continued). "Here we report a homozygous deletion of multiple exons of the MCPH1 gene that was associated with primary microcephaly and intellectual disability; to our knowledge, this is the first such report in a Hispanic family." (PMID 28878824, 2017). "As MCPH1 is also important for brain development, demonstrated by the fact that inherited biallelic MCPH1 mutations result in microcephaly, it is of note that many of the currently identified MCPH1 c.904_916del carrier families also exhibited brain tumors." (PMID 26820313, 2016). "Reflecting these functions, biallelic MCPH1 mutations result in microcephaly and premature chromosome condensation syndrome (MIM #251200)." (PMID 26820313, 2016). "Another autosomal recessive condition characterized by microcephaly with additional craniofacial features and mitotic and chromosomal defects, was later found to also be caused by mutations in MCPH1." (PMID 25870538, 2015). "An observed missense mutation in MCPH1 demonstrated a less severe cellular phenotype and mild microcephaly." (PMID 25951892, 2015). "MCPH1 causes microcephaly in mice and humans and is involved in a diverse array of molecular functions beyond brain development, including DNA repair and chromosome condensation." (PMID 25870538, 2015). "A missense mutation has been reported in MCPH1 gene demonstrating less severe cellular phenotype and mild microcephaly." (PMID 21668957, 2011). "Mutations in the human gene MCPH1 cause primary microcephaly associated with a unique cellular phenotype with premature chromosome condensation (PCC) in early G2 phase and delayed decondensation post-mitosis (PCC syndrome)." (PMID 20169082, 2010). "It's reported that microcephalin/MCPH1 is one of the causative genes responsible for the autosomal recessive disorder primary microcephaly." (PMID 20459802, 2010). "Indeed, mutations in MCPH1 associated with primary microcephaly autosomal recessive, and CHI autosomal recessive are rare." (PMID 38463519, 2024). "Additionally, some of the identified genes correspond to genes implicated in the etiology of microcephaly when mutated, such as MCPH1." (PMID 37427375, 2023). "Importantly, the microcephaly phenotype of MCPH1mt/mt monkeys closely resembles that caused by mutant human MCPH1." (PMID 38025664, 2023). "This is consistent with PCC in MCPH1-deficient microcephaly patients." (PMID 35992200, 2022). "These cases include our proband and a report in which MCPH1 may act as a contributing cause of microcephaly through interaction with a biallelic TRAPPC9 variant." (PMID 35456440, 2022). "These mice were viable and showed a microcephaly phenotype associated with a thinner neocortex and premature differentiation of neuroprogenitors, due to MCPH1-TrCP2-Cdc25 mediated premature mitosis entry and the switch of division mode from symmetric to asymmetric." (PMID 33542216, 2021). "Indeed, most of MCPH1 mutations identified in microcephaly patients affect the BRCT domain, which possibly interacts with some other part of condensin II once MCPH1 has been recruited via its SLiM." (PMID 34850681, 2021). "MCPH1 mutations are known to give rise to microcephaly and CA18." (PMID 32681070, 2020). "Microcephalin-1 (MCPH1) exists as 2 isoforms that regulate cyclin-dependent kinase-1 activation and chromosome condensation during mitosis, with MCPH1 mutations causing primary microcephaly." (PMID 30303738, 2019). "Mutations in the microcephalin gene (MCPH1) are linked to microcephaly." (PMID 31324005, 2019). "MCPH1 gene, mutated in primary microcephaly, regulates cell progression into mitosis." (PMID 29026105, 2017). "MCPH1 is a gene expressed during fetal development and mutations in MCPH1 produce microcephaly." (PMID 29209173, 2017).
microcephaly (continued). "Many genes have been implicated in the development of microcephaly (summarized inTable 1) includingASPM,MCPH1,CDK5RAP2,CEP152,CENPJ,WDR62,STIL,CASC5,CEP135,ZNF335,PHC1,CDK6, with many of them contributing to centrosome and spindle protein dysfunction during mitosis." (PMID 26535115, 2015). "MCPH1 may be a common denominator in the pathway causing microcephaly, encompassing the spectrum of both environmental and genetic forms of microcephaly." (PMID 25870538, 2015). "Therefore, a defect in neurogenic mitosis, which is probably the reason for the microcephaly in humans bearing MCPH1 mutations, may have only a marginal impact on the formation of mouse brain, that could remain undetected by the methods applied." (PMID 20169082, 2010). "Trimborn M., Schindler D., Neitzel H.H.T. Misregulated chromosomecondensation in MCPH1 primary microcephaly is mediated bycondensin II." (PMID 39280843, 2024). "In contrast, Mcph1 (microcephaly, primary autosomal recessive 1, ΔREC = −3515%), involved in determining the mitral valve diameter and DNA-damage signaling and repair, and Aldh3a2 (ΔREC = −1559%) had the largest reduction in the expression control." (PMID 38534766, 2024). "Mcph1−/− mice display microcephaly with a reduction in brain thickness of about 40% in KO mice compared to WT (110.2 μm vs 63.2 μm, p < 0.0001)." (PMID 38605277, 2024). "MCPH1 (microcephalin 1), also known as BRIT1 (BRCT-repeat inhibitor of hTERT expression 1), plays a crucial role in the enlargement of the primate brain, and its mutation leads to microcephaly accompanied by mental retardation." (PMID 38025664, 2023). "Ablation of Mcph1 in mice resulted in elevated genomic instability due to defective homologous recombination repair and mimic microcephaly phenotype." (PMID 36831309, 2023). "Although microcephaly at birth is the pathognomonic sign of MCPH1, in the literature neonatal evaluation was only available for 12 families; 9 of which had proper OFC measurements that ranged between −1.5 and −5 SD." (PMID 35456440, 2022). "Since neural progenitors have a high proliferative index and rely heavily on DNA repair to correct replication errors, impairment of the DNA damage response properties of MCPH1 have also been considered in the pathogenesis of microcephaly." (PMID 35456440, 2022). "In order to study the reasons behind the primary microcephaly phenotype of Mcph1-Δe8 mice, we analyzed the embryonic cortex at the middle stage of neurogenesis, namely E15.5." (PMID 36078123, 2022). "It was proposed that the MCPH1 defect acted as a modifier of a homozygous variant in TRAPPC9, a gene usually associated with postnatal microcephaly, which was heterozygous in the unaffected sister." (PMID 35456440, 2022). "Our study demonstrates that the central domain of MCPH1 represses microcephaly, and is essential for gonad development in mammals." (PMID 36078123, 2022). "The mutation spectrum in the N-terminal domain of the MCPH1 protein, strongly suggests an important function of N-terminal BRCT domain in preventing the microcephaly phenotype." (PMID 33542216, 2021). "Strikingly, Mcph1-ΔBR1 mice completely recapitulate the brain developmental deficits of Mcph1 null mice (Mcph1-ko and Mcph1-Δ), including primary microcephaly, thinner neocortex with reduced neuroprogenitor pools and premature neuronal differentiation." (PMID 33542216, 2021). "We also examined the expression of other microcephaly-related genes: Mcph1, Cdk5rap2, and Aspm that were involved in germ cell maintenance, but we did not detect significant differences in their mRNA expression with WDR62 deficiency." (PMID 34059773, 2021).
microcephaly (continued). "PCC is a prominent cellular characteristic of both human microcephaly patients and the Mcph1-Δ mouse model." (PMID 33542216, 2021). "MCPH1 (BRIT1), the first gene found to cause microcephaly, plays an important role in controlling mitosis, centrosome separation, and DNA damage repair." (PMID 32121580, 2020). "Our work unravels an essential role for MCPH1 in telomere replication and repair, connecting primary microcephaly with telomere dysfunction." (PMID 33203878, 2020). "We report on two siblings with microcephaly and severe ID in whom exome sequencing revealed homozygous mutations in two genes, TRAPPC9 and MCPH1." (PMID 29693325, 2018). "We here report on two siblings with severe ID, microcephaly and hypoplasia of the corpus callosum, a homozygous TRAPPC9 mutation, and a homozygous MCPH1 truncation of BRCT3, and their normal sister with the homozygous MCPH1 mutation only." (PMID 29693325, 2018). "In any case, in view of the similarities with MCPH1, it would be interesting to include Cfdp1 gene in the sequencing panels for microcephaly and related human disorders." (PMID 28367969, 2017). "These mutant mouse lines have been successful in recapitulating the features of primary microcephaly and PCC caused by mutations in MCPH1 in humans." (PMID 25870538, 2015). "The first study demonstrating a microcephaly phenotype in a Mcph1 null mutant mouse model was generated by targeted deletion of Mcph1 exon 4–5 (Mcph1tm1.1Zqw)." (PMID 25870538, 2015). "MCPH1 and MCPH5 are two of ten microcephaly genes identified, which are implicated in autosomal recessive primary microcephaly (MCPH)." (PMID 24830737, 2014). "Recently, two research articles claim the success in generation of mouse model for MCPH1 related primary microcephaly." (PMID 21668957, 2011). "The discovery of Mcph1 involvement in cytokinesis suggests that abnormalities in cytokinesis may play a more prominent role in primary microcephaly than previously thought." (PMID 38605277, 2024). "Finally, the dissection and understanding of the causal mutations in human MCPH1 using more robust and feasible model systems, which even closely reassemble human patients, such as human or primate brain organoids, may provide insight into the etiology of microcephaly and cognitive disorders." (PMID 35053391, 2022). "Mutations in microcephaly genes like assembly factor for spindle microtubules (ASPM), CDK5 regulatory subunit associated protein 2 (CDK5RAP2), microcephalin 1 (MCPH1), and centromere protein J (CENPJ) underwent pervasive positive selection during human evolution." (PMID 36550402, 2022). "Unfortunately, determining whether birth sex correlates with the severity of microcephaly in MCPH1 can be problematic, because most studies only offer a generic clinical description at the pedigree level rather than at the individual level." (PMID 35456440, 2022). "Thus, the altered cell division mode in neuroprogenitors from Mcph1-del and Mcph1-ΔBR1 embryonic brains is responsible for the microcephaly phenotype in these models." (PMID 36078123, 2022). "Therefore, initially, microcephaly or MCPH1 was extensively studied for its role in the DNA damage response (DDR), including DNA repair, cell cycle checkpoint activation, apoptosis, and transcription." (PMID 35053391, 2022). "It has been shown that it is primarily condensin II, not condensin I, that is involved in MCPH1-deficient microcephaly." (PMID 35992200, 2022).